IL13 (interleukin 13)
Diseases named in the same sentence as IL13 in open-access papers (continued):
Sharing a sentence is not in itself a finding about the gene and the disease.
tumor (continued). "In contrast, IL-4/IL-13 stimulation promotes the M2 phenotype that is characterized by the upregulated expression of arginase 1 (Arg1), which metabolizes L-arginine to various tumor-supporting factors (e.g., L-ornithine and polyamines)." (PMID 37108657, 2023). "In vitro coculture assays at high tumor burden establish that second-generation IL13-BBζ or IL13-28ζ outperform first-generation IL13ζ and third-generation IL13-28BBζ CAR designs, with IL13-BBζ providing superior CAR proliferation and in vivo antitumor potency in human xenograft mouse models." (PMID 36968221, 2023). "Together with IL-13, IL-4 may also promote MDSCs to inhibit anti-tumour immunity as shown recently where MDSC-mediated CD8+ T cell suppression is critically dependent on IL-4 and IL-13 signalling." (PMID 37455828, 2023). "As revealed by in vitro studies, tumor growth could be directly enhanced by IL-4 and IL-13 through the activation of their receptors on epithelial cells." (PMID 37835465, 2023). "Th2 cells release IL-5, IL-4, and IL-13, resulting in tumor cell growth and metastasis." (PMID 36703939, 2023). "Furthermore, IL-13 manufacture by type II NKT cells has been reported to contribute to the maintenance of CD11b+Gr-1+MDSCs via the IL-13R-STAT6 pathway in tumor-bearing mice." (PMID 37152373, 2023). "Similarly, IL-33 administration increased tumour-infiltrating IL-13+ ILC2s, MDSCs, and Tregs, and correlated with reduced NK cell cytotoxicity and accelerated tumour growth and metastasis to the lung and liver." (PMID 37455828, 2023). "Following the same rationale as with IL-4, tumor cells have been engineered to secrete IL-13." (PMID 36980536, 2023). "After IL-13 addition, PTP1B associates with IL13Rα2 Tyr369 to promote Src activation, which in turn activates PI3K through FAM120A, a scaffold protein promoting cell adhesion, migration, invasion, proliferation and survival in tumor cells." (PMID 37963919, 2023). "Some evidence suggests that Reed–Sternberg cells secrete IL-13, which could have implications for altering the tumor microenvironment, impacting the immune response, and influencing tumor cell survival." (PMID 37958472, 2023). "In addition, there is evidence that STAT6 can be activated by IL-4 and IL-13 produced by oncogenic Kras driving cells in the tumor microenvironment, and then target cMyc to drive metabolic reprogramming." (PMID 37175092, 2023). "Consistently, intense IL-13 staining in breast TILs was observed in tumor cells which, along with the expression of phosphorylated signal transducer and activator of transcription-6 (pSTAT6), suggested that IL-13, in fact, delivers growth signals to cancer cells." (PMID 37835465, 2023). "Indeed, mice treated with IL13-BBζ CAR T cells exhibited long-term tumor-free survival in >60% of mice after 152 days." (PMID 36968221, 2023). "Given the association of the pro-tumoral IL-25-ILC2 axis with MDSCs, and the expression of Il4ra and Il13ra1 by M-MDSCs, we sought to investigate whether ILC2-derived IL-4 and IL-13 promote MDSC function to suppress anti-tumor immunity." (PMID 35658010, 2022). "The a-GalCer-loaded whole tumor vaccine primes iNKT in the lung-draining lymph nodes with the release of cytokines, including IL-4, IL-13, and IFN-γ, into the serum and is effective against established intracranial tumors but requires depletion of regulatory T cells (Treg)." (PMID 35163235, 2022). "However, the tumor microenvironment is usually infiltrated by M2 cells arising from the influence of IL-4, IL-10 and IL-13." (PMID 35741450, 2022). "In contrast, M2 macrophages, which are stimulated by IL-4 and IL-13 (produced by T-helper 2 cells), play a critical role in tumor initiation, proliferation, metastasis, and immune evasion, and express anti-inflammatory elements, such as IL-10 and transforming growth factor (TGF)-β." (PMID 35844605, 2022).
tumor (continued). "Experimental IL-25-signaling blockade (using the D9.2 clone which also blocks human IL-25R) inhibited ILC2 production of IL-4 and IL-13, limiting the suppressive capacities of MDSCs, thereby permitting the liberation of anti-tumor T cell and IFNγ-mediated immunity and reduced CRC." (PMID 35658010, 2022). "Current studies have shown that M1 macrophages have the ability to enhance the activation of inflammatory factors and phagocytose invading pathogens, while M2 macrophages have the opposite function, inhibiting immune functions and promoting tumor formation through IL-13." (PMID 35732647, 2022). "Moreover, Th2 cells were thought to promote tumor progression by secreting cytokines such as IL-4 and IL-13." (PMID 36139554, 2022). "Similarly, IFN-γ promotes polarization of macrophages to M1 anti-tumor phenotype, while the presence of cytokines, such as interleukin (IL)-4, IL-10 and IL-13 stimulate M2 TAMs with pro-tumor phenotype." (PMID 35268568, 2022). "Additionally, IL-4, IL-5, and IL-13 have been demonstrated to accelerate tumor proliferation and metastasis." (PMID 35546682, 2022). "In vehicle-treated UM samples, a significant negative correlation was observed between IL-6 secretion and patient age, IL-13 secretion and tumour thickness, between VEGF-A secretion and largest ultrasound height (LUH), and between PlGF secretion and chromosome 8 alterations." (PMID 36698840, 2022). "In contrast, we observed a significant decrease in IL5, IL10, IL13, and IL6 levels, which are typically associated with tumor-promoting type 2 immune responses, which are known to support tumor growth, metastatic dissemination, and tumor evasion of immune surveillance." (PMID 35715953, 2022). "The hILC2s secret IL-13 to activate MDSCs which could inhibit anti-tumor immunity, and MDSCs, in turn, produce IL-13 to enhance immunosuppressive activity further." (PMID 36246629, 2022). "We found potent IL-13 production by ILC2s localizing in the lungs of 4T1/LM4 tumor-bearing mice." (PMID 35805039, 2022). "Cytokine secretion, such as interleukin-4 (IL-4), IL-5, IL-9, IL-13, and amphiregulin (Areg), by type 2 innate lymphoid cells (ILC2s) is indispensable for homeostasis, remodeling/repairing tissue structure, inflammation, and tumor immunity." (PMID 35592688, 2022). "Interestingly, type 2 cytokines promote tumour metastasis and contribute to chemoresistance, and miR‐126 has been shown to promote tumour angiogenesis via a TH2‐dependent IL‐13 release mechanism, in a model of breast tumour metastasis." (PMID 35344301, 2022). "Moreover, the LDhi HCC cell line expressed a higher level of type II IL-4 receptor, which promoted tumor proliferation through binding IL-4 or IL-13." (PMID 35721518, 2022). "In addition, other factors such as VEGF, TGF-β, IL-1β, IL-13, Granulocyte-macrophage colony-stimulating factor (GM-CSF) and prostaglandins produced by tumour cells (and other cells of the TME), impact in DCs differentiation and/or maturation." (PMID 35406451, 2022). "The M2-like phenotype typical for TAMs is induced by Th2-derived cytokines among which IL-13 plays a central role; therefore, targeting IL-13 receptors/ligands in the tumor microenvironment can inhibit M2 polarization and ultimately reduce tumor burden." (PMID 35450036, 2022). "Moreover, Th2 and Th17 helper lymphocytes secrete numerous cytokines (including IL-4, IL-5, IL-13, IL-17, IL-21 and IL-22) that contribute to increased tissue inflammation and thus stimulate tumor growth." (PMID 35741450, 2022). "Furthermore, Th2-derived cytokines such as IL-4 and IL-13 promote tumor progression by inducing M2 macrophage polarization." (PMID 35769911, 2022). "CSCs can not only transform into cancer cells and enhance their resistance to chemoradiotherapy, but also secrete immunosuppressive cytokines such as transforming growth factor-β (TGF-β), interleukin-6 (IL-6), IL-10, and IL-13, which can induce immune evasion of tumor cells." (PMID 36176299, 2022).
tumor (continued). "Genetic overexpression of IL-33 led to increased tumour burden and expression of Il4, Il5 and Il13 in Th2 cells, and this correlated with increased tumorigenesis in the Apcmin/+ mice, while genetic deficiency of IL-33 reduced overall tumour Il4 and Il13 expression." (PMID 36263033, 2022). "Tumor M-MDSCs expressed Arginase 1 (Arg1), consistent with a suppressive phenotype, and the genes encoding the IL-4Rα and IL-13Rα1 receptor subunits, suggesting their potential ability to respond to ILC2-derived cytokines IL-4 and IL-13." (PMID 35658010, 2022). "They activate myeloid-derived suppressor cells by secreting IL-13, which may reduce the expansion of Tregs in the lungs of tumor-bearing mice, while promoting the proliferation of CD4+T cells and CD8+T cells." (PMID 35592688, 2022). "Immunosuppression was observed by eosinophils-derived indoleamine 2,3-dioxygenase (IDO) (inhibition of effector T cells) and by an increasing of IL-4 and IL-13-expression by eosinophils via TSLP leading to conversion of macrophages into tumour-promoting activation state." (PMID 35406451, 2022). "Kaplan-Meier survival analysis demonstrated improved survival for mice treated with IL13 WT and IL13-variant CAR T cells, and by day 150, the mice treated with WT and variant CAR T cells had similar numbers of tumor-free and tumor-relapsed mice." (PMID 35939683, 2022). "SMAD4 plays a critical role in tumor progression and induces proinflammatory cytokines, such as interleukin (IL)-5, IL-6, and IL-13, which might induce a tumor-promoting microenvironment." (PMID 33802174, 2021). "Inside the tumor, MCs are able to suppress the anti-tumor immune response by inducing an adenosine-mediated immunosuppressive crosstalk with MDSCs and Tregs and by limiting the adaptive immunity through IL-13 secretion." (PMID 33777750, 2021). "Several cytokines have been reported to support tumor growth in MF such as IL-13, IL-15 and IL-4." (PMID 33941102, 2021). "Overall, IL-13 appears to have a strong effect on modulating tumor progression." (PMID 33922465, 2021). "Tumor-associated macrophages (TAMs) inhepatocellularcarcinoma (HCC) play a prominent role in tumormicroenvironment by presenting M1(induced by IFN γ along with LPS) and M2(induced by IL-4 and IL13) polarization." (PMID 33859517, 2021). "For example, ILC2s’ rapid secretion of inflammatory cytokines IL-13 and IL-4 in human cells have been reported to promote tumor growth by recruitment of monocytic myeloid-derived suppressor cells, immune cells important for the inhibition of anti-tumor immunity." (PMID 34531874, 2021). "Furthermore, we also assessed the pro-tumor effects of IL-13 in vivo by treating tumor-bearing mice with an anti-IL-13 neutralizing antibody." (PMID 33953160, 2021). "IL-4 induces immune deviation from TH1 to TH2 responses, which prevents tumor rejection; IL-10 suppresses the anti-tumor immunity and contributes to tumor immune escape and IL-13 compromises the anti-tumor response by inhibiting IFN-γ secretion and CD8+ T lymphocyte activity." (PMID 35047997, 2021). "Mouse cells express a soluble form of IL13Rα2, which might interfere with the antibody to deplete extracellular IL-13, as secreted IL13Rα2 may bind the antibody in the circulation and could prevent sufficient antibody from binding to the tumor." (PMID 33917458, 2021). "Additionally, IL-13 promotes and facilitates cancer progression by down regulating immune-surveillance and suppressing cytotoxic T lymphocytes responses against the tumours." (PMID 34048465, 2021). "The recruitment of bone marrow-derived monocytes, which differentiate into TAMs, is driven by circulating mediators released by both tumor and stromal cells, including cytokines (IL-1β, IL-10, IL-13, IL-34), osteoactivin, VEGF-A, and colony stimulating factor-1 (CSF-1)." (PMID 33922362, 2021). "Human tumor associated macrophages (TAM) were treated with IL-4 and IL-13 to construct M2-TAM." (PMID 34249713, 2021).
tumor (continued). "Th2 in a tumor microenvironment is a great source of IL-4, IL-5 and IL-13." (PMID 34071442, 2021). "Furthermore, in this same study, it was shown that treatment of animals with IL-13-PE resulted in significant tumor regression and prolonged survival in a murine xenograft model of ACC." (PMID 33591997, 2021). "Moreover, the acquisition of an M2-like phenotype is also caused by the secretion of tumor-derived cytokines such as IL4, IL10, and IL13." (PMID 33562694, 2021). "Th2 (T helper type 2) cells could block T cell-induced tumor rejection by producing Th2 cytokines including IL-4 and IL-13, which can induce the formation of immunosuppressive type 2-polarized macrophages." (PMID 33450900, 2021). "This implied that certain factors in the tumor microenvironment might further boost the upregulation of IL-4 and IL-13 in tumor tissues." (PMID 34194433, 2021). "IL-13 plays a critical role in down-regulation of tumour immunosurveillance and is central to a novel immunoregulatory pathway in which natural killer T cells are induced by tumours to secrete IL-13, which acts through intermediate cells to suppress cytotoxic T cell responses against the tumour." (PMID 34048465, 2021). "We observed the concomitant expression of anti-tumor factors (Il1b, Il13, Ccl7, Il2)." (PMID 34578328, 2021). "In mucosal cancers, tumor growth can cause intestinal barrier damage, which could be part of the reason that IL-17 and IL-13 are initially released and then contribute to the tumor-promoting qualities of the TME." (PMID 33805904, 2021). "Furthermore, the accumulation of MDSCs and M2 macrophages in the TME can be driven by type II NKT cell-produced IL-13, thereby facilitating tumor progression." (PMID 33419310, 2020). "Moreover, detection of inflammatory cytokines showed that Kejinyan decoction downregulated TNF-α, IFN-γ, IL-6, as well as IL-4, IL-13 in tumor microenvironment." (PMID 32943999, 2020). "The involvement of IL-13 in the escape of tumor cells from host immune surveillance is important." (PMID 33343662, 2020). "Interestingly, our qPCR data with validated species-specific primers shows that most of the IL6 was of host origin, while IL13 was expressed by tumor cells." (PMID 33414685, 2020). "Several lines of evidence support a pro-tumor effect of IL-4 and IL-13 in vivo." (PMID 33371444, 2020). "One of such immune subsets is the tumor-associated macrophages (TAMs) which are polarized into M2 macrophage phenotype by IL-10, TGF-β, IL-4, or IL-13 present in the TME, and drive tumor progression by supporting angiogenesis and recruitment of CD4+FoxP3+ T regulatory cells (Tregs)." (PMID 33117354, 2020). "Tumor cells produce IL-13 in response to the host's defense response and defend against apoptosis." (PMID 33343662, 2020). "Moreover, exposure to a target antigen increased cytotoxic efficacy and tumor-killing ability in GSK-3β-inhibited IL13-CAR-T cells." (PMID 32526891, 2020). "Furthermore, many tumor cells release cytokines, chemokines, and growth factors that recruit and induce FOXP3+ Tregs, and induce MDSCs and macrophages to release Th2 cytokines such as Tgf-β, IL-4, IL-10, and IL-13 which suppress anti-tumor immunity." (PMID 32508830, 2020). "Recently, it was shown in vivo that T cell-derived IL-13 promotes RA production by sarcoma cells, which causes differentiation of monocytes in the tumor into cancer-promoting TAMs rather than anti-tumor DCs." (PMID 33171762, 2020). "This suggested that the ILC2/IL-13 axis could counteract the effectiveness of the therapeutic activity of BCG in this tumor." (PMID 32063901, 2019). "Th2 cytokines, such as IL-4 and IL-13, can polarize macrophages into the M2 phenotype, and M2 macrophages function in anti-inflammatory processes, tissue repair and remodeling, parasite clearance, tumor-promoting processes and immunoregulatory processes." (PMID 31192126, 2019). "IL4 and IL13 can activate MDSCs to exert immunosuppression leading to promote tumor growth." (PMID 31540495, 2019).
tumor (continued). "Suppression of IL4 and IL13 as well as IL4Rα and IL13Rα1 might be tumor-suppressive especially in poor prognostic group of cancers expressing both IL4Rα and IL13Rα1 as like IL4Rα+IL13Rα1+ subgroup of CCRCC." (PMID 31540495, 2019). "Pro-tumor: ILC2/IL-13 axis modulate T cell–to-MDSC balance driving an immunosuppressive TME." (PMID 32117199, 2019). "The chitinase family could induce the generation of pro- and anti-inflammatory cytokines and chemokines, such as interleukin (IL)-1β, IL-6, IL-12, and IL-13, making them potential modulators in an inflammatory tumor microenvironment." (PMID 31238895, 2019). "Two NKT subsets have been identified: type I induce the lysis of tumor cells directly via a perforin/granzyme B-mediated mechanism or indirectly via the activation of NK cells and DCs; type II show immunosuppressive activity through the production of IL-13." (PMID 31412566, 2019). "Interestingly, tumor eosinophils, which have been shown to promote M2 macrophage development by secretion of IL-13, were significantly depleted with low-dose CY treatment." (PMID 31921384, 2019). "Importantly, IL-13 is produced by anaplastic tumor cells in BIA-ALCL specimens, which also contain mast cells and eosinophils, further linking Gram-negative bacteria and BIA-ALCL1." (PMID 31316085, 2019). "Pro-tumor functions of TAMs are the result of a macrophage polarization with a particular cytokine profile (macrophage colony-stimulating factor (M-CSF), IL-4, IL-13, IL-10, Prostaglandin E2 (PGE2)) of the TME." (PMID 31547627, 2019). "Th1 cells are pro-inflammatory and express IFN-γ to promote APCs and prime CD8+ cells, while Th2 cells may encourage tumor growth through IL-5 production, although they do recruit eosinophils through IL-4 and IL-13." (PMID 30931508, 2019). "Therefore, it is plausible that ILC2s enhance tumor escape through IL-13-mediated stimulation of MDSCs and M2 macrophages, though direct evidence is lacking." (PMID 31366131, 2019). "Moreover, metformin-treatment lowered expression of IL4, IL10 and IL13 in tumour cells and inhibited metastasis formation and angiogenesis in a mouse model of LLC, a xenograft model of breast and prostate cancer." (PMID 30577495, 2018). "Therapeutic strategies with bacterial toxins like IL13PE38QQR (Pseudomonas Exotoxin), IL13DT (Diphtheria toxin) and IL13 linked nanovesicles were demonstrated to selectively target and eliminate GBM tumors leading to increased survival of the tumor bearing mice." (PMID 29304038, 2018). "Our in vitro and in vivo experiments with peripheral nerve sheath tumor cells and animal models clearly suggest that targeting the IL13Rα2 with IL13 conjugated liposomes will increase the accumulation of the drug in the tumor and subsequently decrease the tumor burden." (PMID 29304038, 2018). "Furthermore, in a spontaneous mouse model of mammary tumorigenesis, intratumoral CD4+ T cells produced cytokines, such as IL-4 and IL-13, which favor the activation and polarization of tumor-promoting immune cells, such as TAMs." (PMID 30355585, 2018). "Subsequently, the recruited monocytes transform into TAMs stimulated by cell factors (like macrophage colony-stimulating factor (M-CSF), vascular permeability factor (VEGF)-1, IL-4, IL-10, IL-13), and then, tumor angiogenesis is induced by TAM-secreted angiogenesis factors." (PMID 29458367, 2018). "In addition, neutralization of ST2Lsignificantly decreased Treg cells and ST2L+Treg both in spleen and in tumortissue of tumor-bearing mice (Figure 5Eand F) and inhibited the protein levels of IL-4, IL-10, and IL-13." (PMID 29950152, 2018). "For example, a report has shown that IL-13 may suppress cancer-directed immunosurveillance and increase tumor metastasis." (PMID 30643796, 2018). "Moreover, acquisition of an M2-like phenotype is also caused by secretion of tumour-derived cytokines such as IL4, IL10, and IL13." (PMID 29065107, 2017).